IL6 (interleukin 6)
Diseases named in the same sentence as IL6 in open-access papers (continued):
Sharing a sentence is not in itself a finding about the gene and the disease.
COVID-19 (continued). "On the other hand, lower circulating levels of IL-6, TNF-α, IL-α, and CCL4 were observed in the asymptomatic group of pregnant women with COVID-19 than healthy pregnant women." (PMID 36016660, 2022). "Cytokine profiles of PBMCs showed significantly lower levels of GM-CSF, IFN-γ, IL-6, IL-9, IL-10, IL-17A, and TNF-α (p < 0.0001) in COVID-19 ICU patients." (PMID 36363785, 2022). "Single-cell RNA sequencing (scRNA-seq) shows classical monocytes as the primary source of cytokines and chemokines in severe COVID-19, such as CCL2, CXCL8, IL-6, TNF-α." (PMID 35401519, 2022). "These agree with the findings of the present study, which showed a significant increase in IL6, D-dimer, CRP, and serum ferritin in both patient groups as compared to controls and in patients with severe COVID-19 as compared to moderate cases." (PMID 36359290, 2022). "Several studies have demonstrated the presence of inflammatory mediators, such as increased levels of pro- and anti-inflammatory interleukins (IL-1, IL-2, IL-6, IL-10) and tumor necrosis factor-alpha (TNF-α) in the serum of COVID-19 patients." (PMID 36077138, 2022). "In this study, we evaluated the expression of the immune–inflammatory mediators IL-1β, IL-6, IFN-β, and IFN-λ in postmortem lung specimens (i.e., the natural site of SARS-CoV-2 infection) of patients who died because of severe COVID-19 and control subjects." (PMID 36422642, 2022). "We incubated HLMVEC for 24 hr with 30% patient plasma obtained from severe COVID-19 patients who were admitted to the ICU and analyzed the cells for the expression of E-selectin, VCAM-1, ICAM-1, and IL-6." (PMID 35837388, 2022). "It has been reported that levels of proinflammatory cytokines (IL-2, IL-6, IL-7, IFN-I, IFN-II) are strictly correlated with the viral load and lung injury in patients with severe COVID-19, reflecting the severity and the prognosis of this disease." (PMID 36289890, 2022). "We demonstrated a correlation of CRP, IL-6, PCT, leukocyte count, and LDH with the severity of COVID-19." (PMID 35676519, 2022). "Inflammatory organ damage can result among sick individuals with critical COVID-19 or patients having an extremely greater expression of inflammatory markers including ferritin, C-reactive protein (CRP), interleukin-1, and interleukin-6." (PMID 35242118, 2022). "The proposed pathogenesis for this common coexistence is elevated levels of IL-6, tumor necrosis factor α (TNF α), and granulocyte-macrophage colony-stimulating factor resulting in COVID-19 induced cytokine storm." (PMID 35865966, 2022). "In agreement, COVID-19 severe patients show increased plasma concentration of IFN-α, IFN-γ, IL-6 and TNF-α early after the disease onset." (PMID 35844604, 2022). "Specifically, postmortem autopsies from spleens of deceased COVID-19 patients showed that CD8+ T-cells were extremely low in all patients, and inflammatory cytokines (IL-6, IL-8, and IL-10) were increased, along with severe spleen tissue damage." (PMID 36389664, 2022). "The present research revealed that there are correlations between chest CT features of patients with COVID-19 and changes in CRP, procalcitonin, IL-6, and NLR parameters; thus the latter can be used to assess disease severity." (PMID 35893392, 2022). "IL6 and IL8 together can identify ∼50% of the patients with moderate or severe COVID-19 progression even when the severe symptoms of the disease progression are not yet apparent." (PMID 36518355, 2022). "In association with clinical observations, the kinetic measurement of IL-6 during SARS-CoV-2 infection is a crucial tool to predict the prognosis and outcome of patients with COVID-19." (PMID 35741183, 2022). "The roles of IL-6 and IFN-γ are both important and well described, and both are elevated greatly in COVID-19 patients." (PMID 36662492, 2022).
COVID-19 (continued). "In cluster 1, IL6, IL1B, TNF, and CCL2 of the top ten key targets were enriched in COVID-19 adverse outcomes pathway, indicating the exacerbation of COVID-19 inflammation on DILI." (PMID 35979235, 2022). "Inflammatory biomarkers, such as IL-6 and CRP, are predictive biomarkers in COVID-19 patients and were significantly increased in the SARS-CoV-2-positive group compared to the control group." (PMID 35064792, 2022). "MMP-7, TGF-β, CCL2, CCL-3, CXCL-10, G-CSF, IFN gamma, IL-10, IL-2, IL-4, IL-6, IL-7, TNF-α, IL-6, and IGF-1 were studied for their correlation to lung involvement in COVID-19 patients." (PMID 36286038, 2022). "Elevated IL-6 levels have been identified in several severe disorders such as sepsis, acute respiratory distress syndrome (ARDS), and most recently, COVID-19." (PMID 35385549, 2022). "Induction of CD39 expression occurs upon cellular activation and is regulated by hypoxia, oxidative stress, and inflammatory cytokines such as IL-6 and TNF-α, which are frequently increased in COVID-19 patients." (PMID 36248842, 2022). "The network pharmacology showed CHM formulas affected several inflammation-related proteins for COVID-19, including IL-10, TNF-α, IL-6, TLR3, and IL-8, in which Dexamethasone and Aspirin covered only IL-10 and TNF-α." (PMID 35890093, 2022). "After stimulating myeloid blood cells with R848, we observed that multiple myeloid subsets from COVID-19 patients had lower levels of IFNβ and higher levels of TNF, IL-6, IL-12, CCL3, and CCL4 than cells from healthy controls." (PMID 36085197, 2022). "Recent IL-6 antagonists, especially tocilizumab, have been repurposed for the remission of CRS in COVID-19 patients as adjunctive therapy where multiple case series have suggested a potential role for tocilizumab." (PMID 36676678, 2022). "Since no molecular studies were available for CAM patients, we focused on studies featuring COVID-19 severity and selected nuclear factor erythroid 2-related factor 2 (NRF2), interleukin-6 (IL-6), and IL-15 as the candidate genes for this analysis (30, –, 33)." (PMID 36377893, 2022). "In severely affected COVID-19 patients with ARDS at ICU, the anti-inflammatory IL-10 and GDF15 were increased, positively and negatively correlated with pro-inflammatory IL-6 and lymphopenia, respectively." (PMID 36140453, 2022). "For example, the study by Del Valle el al. is consistent with our results, which reported the higher levels of IL-6 and TNF-α in COVID-19 male patients than healthy subjects." (PMID 36381078, 2022). "A significant increase in 40 analytes was identified, including IL-1, IL-2, IL-6, IL-10, IFN-γ, and TNF-α, which are important proinflammatory cytokines that have been established in patients with COVID-19." (PMID 36290634, 2022). "The levels of the pro-inflammatory cytokines GM-CSF, IL-6, IL-15, and IFN-α were higher in mild-moderate COVID-19, compared to healthy controls, with a further increase in severe COVID-19." (PMID 35529862, 2022). "We observed that CXCL8 (AUC 0.98) and VEGFA (AUC 0.94) were particularly good at predicting COVID-19 outcomes within hematologic cancer patients, while CXCL8 (AUC 0.89) and IL-6 (AUC 0.88) were good predictors for solid tumor patients." (PMID 36700209, 2022). "Previous studies have reported increased concentrations of IL-6,10 and TNF-α in severe cases of COVID-19." (PMID 36138753, 2022). "Inflammatory markers, such as IL-6, D-dimer, CRP, and/or ferritin, are believed to correlate directly with mortality in COVID-19." (PMID 36289811, 2022). "Age was the strongest contributor to the progression from common type to severe type COVID-19, followed by dyspnea, CRP, IL-6 and lymphocyte count." (PMID 35037900, 2022). "Studies indicate that IL-6, TNF-α, and IFN-γ has become a significant feature of COVID-19 patient deterioration." (PMID 36034662, 2022).
COVID-19 (continued). "The goal of this study is to investigate the predictive value of trends in repeated measurements of CRP, PCT, IL-6, and suPAR on mortality in patients admitted to the ICU with COVID-19." (PMID 35859926, 2022). "LA itself is a precursor of arachidonic acid, which is elevated in our COVID-19 ICU patients, those with elevated IL-6, and mice given LA." (PMID 35502320, 2022). "While IFN-α and IFN-β were undetectable, IL-10, IL-17A and IL-18 were variably detected in COVID-19 BALF, with higher RNA and/or protein levels of IL-6, MCP-1 and IL-33 and lower IL-6 receptor (IL-6R) observed in COVID-19 BALF compared to healthy BALF19,20." (PMID 35589689, 2022). "mRNA levels of ADAM17, IFITM3, IL6, CXCL10, CXCL11, IFNG and TYK2 were increased in PBCs of COVID-19 patients (n = 73) compared with controls (n = 47), independently of sex." (PMID 36009555, 2022). "A variety of cytokines and chemokines including IL-1α, IL-6, IP-10, MCP-1, MIP-1α and IFN-γ had been found to be significantly elevated in the serum of COVID-19 patients." (PMID 35365215, 2022). "However, the relationship between IL-6 and coagulopathy remains unclear in COVID-19 progression." (PMID 37841828, 2022). "Inflammatory markers, especially IL-6, CRP, Procalcitonin, and ESR, have been positively correlated with the severity of COVID-19." (PMID 36366295, 2022). "Recent data have indicated that patients with COVID-19 also had high concentrations of serum cytokine profiles, such as TNF-α, IL-1, IL-6, and IFN-γ." (PMID 35346253, 2022). "For instance, elevated levels of interleukin (IL)-6, IL-1, TGF-β, and TNF-α have been detected in COVID-19 patients." (PMID 35016612, 2022). "The top four highest scoring cytokines (MCP-3, IL-8 IL-6, and MCP-1) reported in COVID-19 patients with high mortality are all transcriptionally regulated by NF-κB." (PMID 35890406, 2022). "Severe COVID-19 manifested as ARDS with elevated pro-inflammatory cytokines, involving TNF-α, IL-6, IL1B, and CCL2." (PMID 35227280, 2022). "To date, the only drugs that have reduced mortality in COVID-19 ARDS are anti-inflammatory/immunosuppressive drugs: dexamethasone, IL6 antagonists (tocilizumab or sarilumab) and the JAK inhibitor baricitinib." (PMID 35860245, 2022). "Previous studies have shown that lncRNA MALAT1 can regulate IL-6 and NLRP3 inflammatory cytokines, and lncRNA TUG1 plays an important role in the anti-inflammatory response to COVID-19 by blocking IL-6 cytokines." (PMID 36204652, 2022). "Increased expression of inflammatory SASP factors such as IL6, MCP1, and CCL2 are known to mediate excessive inflammatory response and cytokine storm of severe COVID-19 patients." (PMID 36400883, 2022). "Multivariate linear regression analysis of IL-6 and IL-10 according to FT3 with adjustment for age, sex, and BMI in ward hospitalized COVID-19 patients." (PMID 36440226, 2022). "Some of these biological therapies, such as IL-6, IL-1 and TNF inhibitors, showed promising results also in COVID-19 patients." (PMID 35563218, 2022). "In patients with severe COVID-19, the production of TNF-α and IL-6 is sustained by circulating monocytes." (PMID 36056419, 2022). "We also described the correlation of inflammatory cytokine levels (resistin, IL-6, IL-8, IL-15, MCP-1 and TNF-α) with clinical variables related to a worse COVID-19 prognosis." (PMID 35330391, 2022). "Since IL-6 was found elevated in COVID-19, it is of great interest to explore the combined effect of IFN-γ, TNF-α, with IL-6 on inflammatory cell damage." (PMID 36034662, 2022). "Consistent with prior studies, we found that IL-6, IL-8, IL-1RA, CXCL-10 distinguished healthy controls from both moderate and severe COVID-19 cases." (PMID 35421120, 2022). "As described in several studies, we observed increased circulating levels of inflammatory cytokines such as IL-6, IP10, and GM-CSF in hospitalized patients compared with patients with mild COVID-19 — in particular, if they had needed admission to ICU." (PMID 35380990, 2022).
COVID-19 (continued). "In contrast, we found that plasma IL-6, IFN-α, IFN-γ, IL-1β, TNF-α, IL-10, IP-10, MIG and MCP-1 levels were significantly higher in severe COVID-19 compared to healthy controls." (PMID 35422799, 2022). "Tocilizumab (TCZ), a recent IL-6 antagonist, has been redeployed as adjunctive treatment for CRS remission in COVID-19 patients." (PMID 36676678, 2022). "Among the enriched significant pathways, the Coronavirus disease-COVID-19-related pathways is the most significant pathway which involved most of the hHub-DEGs notably, CXCL8, EGFR, IL6, JUN, MAPK1, STAT3, TNF, and UBA52." (PMID 36016137, 2022). "Given the importance of IL-6 in inflammation and its recently highlighted implications in COVID-19 pathogenesis we investigated the mechanistic interactions of APEX and its selected constituents with the IL-6 gene expression pathway." (PMID 35624724, 2022). "However, while many authors focused on the potential role of repurposed drugs and cardiac strain/injury in the pathogenesis of COVID-19-associated QTc prolongation, no investigation was specifically designed to explore the discrete impact of IL-6 on this phenomenon." (PMID 35665254, 2022). "Despite showing heterogeneous results in the following randomized clinical trials, IL-6 inhibitors were included in the current NIH COVID-19 guidelines for the treatment of severe and critical COVID-19." (PMID 35887283, 2022). "NK cell hyperactivation, likely driven by IL-6, IL6R and IL-18 is a feature of severe COVID-19 as compared to mild or moderate disease." (PMID 36160152, 2022). "IL-1β, IL-6, IL-8, TNFα and CRP in the hospitalised patients with COVID-19 (n = 76) was higher (all p<0.0001) compared to the healthy volunteers." (PMID 35500008, 2022). "Serum levels of inflammatory cytokines including IL-6, G-CSF, IP-10, MCP1, MIP1A, and TNF are elevated in COVID-19 patients within intensive care units (ICU), which indicates the occurrence of cytokine storm in these patients." (PMID 36458163, 2022). "Despite the suppression of host IFN signaling by SARS-CoV-2 infection, levels of cytokines/chemokines, such as IL-6, IL-8, IP-10, and TNF-α, are significantly elevated in COVID-19 patients." (PMID 35856559, 2022). "Currently, several therapies are used for the COVID-19 treatment to reduce the overwhelmed inflammation and the SARS-CoV-2-mediated activation, such as IL-1β inhibitors, IL-6 inhibitors, JAK-inhibitors, and corticosteroids." (PMID 36148228, 2022). "In this study concentrations of TNF-α, IL-1b, IL-2, IL-4, IL-5, IL-6, IL-8, IL-10, IL-12 p70, GM-CSF, and IFN-γ were determined by a magnetic bead assay in tear film collected from 232 symptomatic COVID-19 patients." (PMID 35508669, 2022). "A recent study using artificial intelligence techniques revealed that genes involved in activation of immune pathways (IL-6, TNF, JAK2, IL-1B, SERPINE1, TGFB1, CD8A, and VWF) serve as major hubs in the COVID-19- thrombocytopenia interactomes." (PMID 35372456, 2022). "In contrast to the cases with severe COVID-19 and MIS-C, IL-6 and IL-1β levels were normal in MIS-A cases." (PMID 35601440, 2022). "A not yet published study showed a long-lasting cytokine signature in patients with prior COVID-19 where IL-1β, IL-6, and TNF-α showed a significant correlation with post-acute COVID-19." (PMID 35883640, 2022). "In conclusion, besides the well-known inflammatory markers CRP and IL-6, a panel of other cytokines such as IP10, sIL2Rα and IL-10 appear as very interesting tools to stratify COVID-19 patients, deserving possible new strategic intervention." (PMID 35563218, 2022). "The percentage of activated (CD69+) total ILCs and activated ILCp positively correlated with serum IL-6 levels and with CXCL10 levels in the COVID-19 patients." (PMID 35159352, 2022). "Cytokine profiles in patients diagnosed with COVID-19 showed marked elevation of T-helper lymphocyte type 1, IFN-γ, and inflammatory cytokines IL-1β, IL-6, and IL-12 for at least 2 weeks after disease onset." (PMID 35850685, 2022).
COVID-19 (continued). "Using >300 pg/ml as the cut-off for IL6 and >200 pg/ml IL8 in our study, 50% of the patients with progressive (moderate or severe) COVID-19 can be identified for early therapeutic intervention." (PMID 36518355, 2022). "These targeted therapies are used to treat both inflammatory diseases with more aggressive phenotypes, and severely ill patients with COVID-19, considering the major contribution of TNF and IL-6 to the cytokine-storm syndrome observed in critical patients." (PMID 35770002, 2022). "Similar to COVID-19-related inflammation, CQ has shown rescuing effects against brain neuroinflammation by suppressing the inflammatory cytokines, such as TNF-α, IL-6, and IL-12, in LPS-challenged mice." (PMID 35455977, 2022). "Its inhibition leads to the reduction of inflammatory cytokines and chemokines, such as TNFα, IL-1, IL-6 and MCP-1, which are thought to be primarily involved in exuberant systemic inflammatory responses in COVID-19 patients." (PMID 35164139, 2022). "The lung tissues of patients with COVID-19 were enriched with CCR6 and IL-17A co-expressing cells, and high concentrations of IL-6, IL-17A, GM-CSF, and IFNγ were found in the liquid fraction of BALF." (PMID 35632823, 2022). "The results showed an elevated concentration of IL-1β, IL-6, TNF-α, IL-2R, IL-17, and IL-10 cytokines in the serum of COVID-19 patients." (PMID 35842705, 2022). "These connections make the interactions of the inflammatory markers, specifically IL-6 and TNF-α with testosterone and inhibin B in COVID-19 patients an intriguing target of further exploration by immunologists, physiologists and drug researchers." (PMID 36381078, 2022). "(2020) noted that elevated serum levels of IL-6, IL-8, and TNF-α in COVID-19 patients at the time of hospitalization were strong and independent predictors of patient survival." (PMID 35846757, 2022). "Persistent proinflammatory cells [IL-1, IL-6, and Tumor Necrosis Factor-α (TNF-α)] and altered cytokine production is suspected to have occurred during persistent inflammation in post COVID-19 conditions, revealed by a cytokine profiling study." (PMID 36698905, 2022). "From this search, we identified 6 cytokines that are critically involved in the pathogenesis of COVID-19 induced ARDS lung injury (IL-1β, IL-2, IL-6, IL-8, IL-10, and TNFα)." (PMID 35033181, 2022). "Different biomarkers have been investigated in COVID-19 as predictor of mortality, including C-reactive protein (CRP), procalcitonin (PCT), interleukin-6 (IL-6), and soluble urokinase-type plasminogen activator receptor (suPAR)." (PMID 35859926, 2022). "Lymphopenia is ubiquitous in COVID-19 patients with significantly decreased absolute counts of T-cells, and increased levels of pro-inflammatory cytokines (e.g. IFN-γ, IL-6, IL-8)." (PMID 36069182, 2022). "Elevated inflammatory biomarkers like C-reactive protein (CRP) and proinflammatory cytokines like interleukin-2 (IL-2), interleukin-6 (IL-6), interleukin-10 (IL-10), gamma interferon (INF), and tumor necrosis factor-alpha (α-TNF) are higher in severe COVID-19." (PMID 38013720, 2022). "Fifth, IL-6 and CRP are the two best performing inflammatory biomarkers to predict ICU admission or death at 30 days in patients with COVID-19." (PMID 35622838, 2022). "Sodium pyruvate impairs inflammatory cytokine production (IL-6, IL-1β, and TNF-α) in macrophages during Influenza A virus infection and has been tested in clinical trials for acute COVID-19 and now Long COVID." (PMID 36070309, 2022). "Hadjadj and colleagues demonstrated that IFN-I signaling was highly dysregulated in severely or critically ill COVID-19 patients, as indicated by low IFN-I and ISGs levels, despite increased levels of TNF-, IL-6-, and NF-κB-driven inflammatory responses." (PMID 36298629, 2022). "Third, levels of inflammatory biomarkers, especially IL-6 and CRP, show high discriminative accuracy to predict the need for hospitalisation in patients with COVID-19." (PMID 35622838, 2022).